JAK3 (Janus kinase 3)
Diseases named in the same sentence as JAK3 in open-access papers (continued):
Sharing a sentence is not in itself a finding about the gene and the disease.
Arthritis (13 papers, 2008 to 2025). Inflammation of a joint. "Monocytes play a crucial role in arthritis pathogenesis, with their activation and chemotaxis being tightly linked to JAK3 signaling." (PMID 40626319, 2025). "Since multiple cytokines whose receptors signal through pathways involving JAK3 have been associated with progression of arthritis, experiments were designed to evaluate the effects of CP-690550 in rodent models of the disease." (PMID 18234077, 2008). "Recently, dual BTK/JAK3 inhibitors have drawn extensive attention in the fields of cancer and arthritis treatment." (PMID 40626319, 2025). "Vaccination with both TLA and TLA-encapsulated niosomes for the first time in adjuvant-induced arthritis ameliorated the disease through diversion of immune system and JAK3 downregulation." (PMID 37389660, 2023). "Mechanistically, Wj1113 inhibits BTK/JAK3 signaling in vivo and alleviates arthritis in joints." (PMID 40626319, 2025). "The prednisolone-treated arthritis group which showed only focal positivity of anti-JAK3 expression (score 1–2) was slightly better than TLA and TLA-encapsulated niosomes groups; however, no statistical significance was seen with them (P = 0.146, 0.409, respectively)." (PMID 37389660, 2023). "Thus, at low doses, this JAK3 inhibitor was shown to enhance experimental autoimmune encephalitis but suppress collagen induced arthritis." (PMID 24603870, 2014). "The efficacy produced by CP-690550 in the rodent models of arthritis may result from its ability to affect signaling of a number of cytokines including IL-2, -7, -15 and -21 as a consequence of JAK3 inhibition." (PMID 18234077, 2008). "The first irreversible BTK kinase inhibitor PCI-32765, which has demonstrated the proof-of-concept for the anti-arthritis efficacy by direct inhibition of BTK kinase, also bears potent activities against BLK, BMX, EGFR, Her2, ITK, JAK3, TEC and others." (PMID 28352114, 2017). "Tofacitinib is a JAK3 inhibitor and demonstrates some JAK1 pathway inhibitory effects in mouse models of arthritis." (PMID 27379204, 2016). "In the arthritis model tissues, the BTK and JAK3 signaling pathways were activated." (PMID 40626319, 2025).
Autoimmunity (12 papers, 2012 to 2025). The occurrence of an immune reaction against the organism's own cells or tissues. "While the asymptomatic parents carry either the CTLA-4 mutation or the JAK3 variant, their son has inherited both heterozygous mutations and suffers from hypogammaglobulinemia combined with autoimmunity and lymphoid hyperplasia." (PMID 29375547, 2017). "The combination of the individually harmless JAK3 and CTLA4 variants results in a TFH cell defect with symptoms such as lymphadenopathy, autoimmunity, and hypogammaglobulinemia." (PMID 37140667, 2023). "Thus, IL-15/IL-15Rα activates the JAK1/JAK3 and STAT3/STAT5 pathways to induce proliferation of T and NK cells, and this mechanism could limit exposure to circulating IL-15, that contributeS to the risk of autoimmunity." (PMID 22888423, 2012). "Although the blockade of JAK3 activity can inhibit NK cell activation, it is still unclear if γc cytokine-driven NK1 phenotype plays a protective or detrimental role during the progression of autoimmunity." (PMID 38106519, 2023).
vitiligo (12 papers, 2023 to 2026). Generalized well circumscribed patches of leukoderma that are generally distributed over symmetric body locations and is due to autoimmune destruction of melanocytes. "According to the research, JAK3 and the cytokines IL-4 have a significant role in the etiology of vitiligo." (PMID 38695020, 2024). "Tofacitinib, a selective JAK1 and JAK3 inhibitor, is effective against vitiligo when administered orally or topically." (PMID 39559368, 2024). "This was the first study focusing on the differential effects between active and stable lesions in patients with active vitiligo treated with a JAK3/TEC family kinase inhibitor on both clinical measures (depigmentation) and molecular signatures." (PMID 39023568, 2024). "In the current study, we demonstrated that T-96 interacted with JAK3 in the CD8+ T cell from vitiligo patients, attenuating IL-2-induced JAK3 phosphorylation." (PMID 37403086, 2023). "The JAK1/JAK3 inhibitor tofacitinib abrogates IL-4 signaling and the differentiation of Th2 cells; moreover, tofacitinib is an effective and well-tolerated therapy option for people with refractory vitiligo, according to numerous research." (PMID 38695020, 2024). "As treatment options evolve, particularly with the emergence of oral Janus kinase inhibitors and dual Janus kinase 3/tyrosine kinase expressed in hepatocellular carcinoma family kinase inhibitor, it is essential to assess population-level safety events in patients with vitiligo." (PMID 41937741, 2026). "Hence, tofacitinib, a JAK3 inhibitor designed to lower IL-4-related Th2 cytokines, may thus be useful in treating certain cases of refractory vitiligo." (PMID 38695020, 2024). "Ritlecitinib, a JAK3 and TEC kinase family inhibitor, has been approved for treatment of patients with AA and is in late-stage development for vitiligo." (PMID 39825945, 2025). "Ritlecitinib is an oral JAK3 and tyrosine kinase inhibitor which is used in the treatment of active non-segmental vitiligo." (PMID 39559368, 2024). "to investigate the effect of ritlecitinib, a JAK3/TEC family kinase inhibitor, on the protein levels of 65 non-segmental vitiligo patients." (PMID 38715599, 2024). "Recent studies indicate that JAK1 and JAK3, but not JAK2, demonstrated higher cutaneous expression in vitiligo skin compared to healthy skin." (PMID 39201060, 2024).
acute megakaryoblastic leukemia (11 papers, 2010 to 2024). Acute megakaryoblastic leukemia (AMKL) is a form of acute myeloid leukemia (AML) that occurs predominantly in childhood and particularly in children with Down syndrome (DS-AMKL). "JAK3 mutations were initially identified in patients with acute megakaryocytic leukemia, and mainly found in T-ALL and NKT lymphoma." (PMID 28410228, 2017). "Recent studies identified activating JAK3 mutations in patients with various hematopoietic malignancies, including acute megakaryoblastic leukemia." (PMID 20149240, 2010). "However, other studies report this mutation as somatic suggesting that loss-of function mutations of JAK3 can be also somatically acquired in other diseases (sporadic hemangioblastomas, Down syndrome, acute megakaryoblastic leukemia)." (PMID 32639993, 2020). "Functional JAK3 mutations in the PTK (Pseudokinase) domains have been identified in acute megakaryoblastic leukemia (AMKL), T-cell prolymphocytic leukemia and NK T-cell lymphoma." (PMID 26980750, 2016). "In contrast, abnormal JAK3 activation is associated with acute megakaryoblastic leukemia (AMKL) and cutaneous T cell lymphoma (CTCL)." (PMID 24170986, 2013). "This mutation in JAK3 has not been reported in PDAC but has been observed in acute megakaryoblastic leukemia." (PMID 26934555, 2016).
asthma (11 papers, 2012 to 2024). "In clinical research, the JAK3 inhibitor tofacitinib has been widely used to treat a variety of diseases, and tofacitinib demonstrates potential as an alternative therapy for asthma." (PMID 35572723, 2022). "Some of them have been reported to be significantly relevant to asthma such as NEAT1 → hsa-miR-139→ JAK3." (PMID 34970542, 2021). "Intriguingly, eosinophilic gastroenteritis patients express high levels of phospho-JAK3, which is coincident with the finding that JAK3 activation is critical for airway eosinophilic inflammation, as in asthma and rhinitis." (PMID 22523564, 2012). "Findings from this study imply a role for JAK3 inhibitors in corticosteroid resistance asthma." (PMID 39194521, 2024). "JAK3 is an upstream signaling pathway of STATs, whose activation promotes the expression of STATs, an airway inflammatory target involved in the pathogenesis and development of asthma." (PMID 35572723, 2022). "In conclusion, our data suggest that PI3K and JAK3 inhibitors showed promising alternative therapeutic activity in asthma, which might significantly counteract the airway inflammation in patients with allergic asthma." (PMID 28293189, 2017). "Recent studies have shown that inhibitors of JAK3 might prove useful in asthma." (PMID 39194521, 2024). "Neutrophils from healthy subjects, severe asthma and COPD patients showed a higher expression of JAK2 followed by JAK3 and in a lesser extent of JAK1, while levels of TYK2 were the lowest." (PMID 35332239, 2022). "In acute model of asthma, PI3K and JAK3 inhibitors, and dexamethasone were found effective in inhibiting infiltration of basophils, macrophages, neutrophils, and lymphocytes into bronchoalveolar compartment." (PMID 28293189, 2017). "There is evidence that treatment of allergic asthmatics with inhaled steroids was able to reverse the high levels of IL-5, IL-13 and IL-9 produced by ILC2s via STAT3, STAT5, STAT6, JAK3 and MEK signaling pathways, which was accompanied by better asthma control." (PMID 39452061, 2024). "Blocking the JAK3 pathway with JAK3 inhibitor PF06651600 in this steroid-resistant murine model inhibited formation of the multipotent ILC2s in vitro and ameliorated Alternaria-induced asthma." (PMID 39194521, 2024). "The elevated levels of JAK2 and JAK3 in neutrophils from COPD and severe asthma patients could explain the efficacy of LAS194046 inhibiting IL-8 and MMP9 release, as well as the inhibition of ROS production that we observed." (PMID 35332239, 2022). "JAK3 is also involved in immunoglobin-E (IgE) class switching, mediating responses of dendritic cells, macrophages and non-hematopoietic lineage cells in asthma." (PMID 28293189, 2017).
T-cell acute lymphoblastic leukemia (11 papers, 2015 to 2025). Acute lymphoblastic leukemia of T-cell origin. "The disease of T-cell acute lymphoblastic leukemia can be caused by mutations in the Janus kinase 3 (JAK3) gene, activity inhibition of which is found to link with abnormal higher phosphorylation level of CMTR1, another type of 2’-O-methyltransferase." (PMID 37065445, 2023). "JAK3 mutations have already been described in megakaryoblastic, T-cell prolymphocytic, natural killer T-cell, and T-cell acute lymphoblastic leukemias." (PMID 27144517, 2016). "A relationship between GLI1 and JAK3 was identified in acute T-cell lymphoblastic leukemia, where their expression levels showed a positive correlation." (PMID 29789566, 2018). "In contrast, increased JAK1 and JAK3 signaling can lead to T-cell acute lymphocytic leukemia in mice." (PMID 30564118, 2018). "This gain-of-function mutation JAK3 (V722I) replaces valine with isoleucine at position 722 inside the pseudokinase domain leading to constitutive JAK3 activation, as described in megakaryoblastic, prolymphocytic and in T-cell acute lymphoblastic leukemias." (PMID 27144517, 2016). "Notably, JAK3 inhibitors have demonstrated clinical benefits in patients with T-cell acute lymphoblastic leukemia." (PMID 40713600, 2025). "JAK1 has been implicated with different kinds of acute leukemia or B-cell lymphoma dependent on mutated sites, JAK2 mutation was usually associated with thrombocytosis, myelofibrosis, leukemia, and lymphoma and increased JAK3 signaling can result in T-cell acute lymphocytic leukemia." (PMID 30564118, 2018). "In T-cell acute lymphoblastic leukemia (T-ALL), HOXA9 acts as an oncogene by cooperating with JAK3/STAT5 at the transcriptional level through upregulating the expression of downstream genes, such as PIM1 and activator protein-1 (AP-1), thereby affecting cell survival and apoptosis." (PMID 31013831, 2019).
COVID-19 (10 papers, 2020 to 2025). A disease caused by infection with severe acute respiratory syndrome coronavirus 2. "Functionally, relevant mutations and polymorphisms in JAK family proteins, including TYK2, JAK1, JAK2, and JAK3, have been associated with diverse immune-related diseases and have now been implicated in COVID-19 severity and susceptibility." (PMID 40410684, 2025). "JAK3, primarily expressed in immune cells, is associated with immunodeficiency syndromes, which may influence COVID-19 outcomes depending on the inflammatory context." (PMID 40410684, 2025). "This review highlights the role of JAK3 in immune and epithelial cells, examines the adverse effects of oral JAK3 inhibitors in COVID-19 and other treatments, and discusses alternative therapeutic strategies for improving patient outcomes." (PMID 40410684, 2025). "The COVID-19 high-stage-specific markers (i.e., FOS, CXCL8, HLAA, JAK3, ICAM1, and H2BC4) were overexpressed in higher-stage samples, that is, increased expression levels of the markers were observed in asymptomatic to critical samples." (PMID 41155463, 2025). "Our work highlighted an increased expression of genes related to the endomembrane system, such as RAB1B, RAB24, RAB32, JAK3, and SELP, in severe COVID-19 patients’ blood samples." (PMID 38262689, 2024). "Three FDA-approved drugs for other indications were repurposed for COVID-19 treatment: Baricitinib, Ruxolitonib, and Tofacitinib, which target JAK1/JAK2, JAK1/JAK2, and JAK1/JAK3, respectively." (PMID 39599762, 2024). "JAK3, ICAM1, and H2BC4 were identified as markers of higher COVID-19 severity." (PMID 41155463, 2025). "Based on our results, we suggest that controlling high-severity-specific markers (FOS, CXCL8, HLA-A, JAK3, ICAM1, and H2BC4) and low-severity-specific markers (IL1B, CD3D, CD4, CCL5, and SNRPB) may prevent COVID-19 progression." (PMID 41155463, 2025). "Inhibits JAK3, JAK1, JAK2, and to a lesser extent TYK2 and inhibits receptor signaling through pairs of JAK2 and because it can suppress the production of different cytokines, such as IL-2, IL-7 and IL-6 can used for patients with COVID-19." (PMID 36111104, 2022). "Although the analysis was limited to only two patients without individual cell-type resolution, in genome browser, up-regulation of IFITM1, ISG15, and JAK3 and down-regulation of RPS18 were observed commonly in post-mortem COVID-19 lung tissues and classical monocytes of severe COVID-19." (PMID 32651212, 2020). "Furthermore, JAK3, JAK2 and TYK2, which are highly activated in COVID-19, may be co-targeted with cytokine-modulatory therapy." (PMID 38389037, 2024).
hepatocellular carcinoma (10 papers, 2018 to 2026). A malignant tumor that arises from hepatocytes. "In September 2023, EMA approved Ritlecitinib, an oral inhibitor of JAK3 and tyrosine kinase expressed in the hepatocellular carcinoma family (TEC), for the treatment of severe AA in adults as well as in adolescents aged 12 years and older." (PMID 40507644, 2025). "Ritlecitinib is an oral inhibitor of JAK3 and tyrosine kinase expressed in hepatocellular carcinoma (TEC) family kinases." (PMID 39812238, 2025). "Ritlecitinib, an inhibitor of Janus kinase 3 and tyrosine kinase expressed in hepatocellular carcinoma family kinases, is in development for inflammatory diseases." (PMID 37561322, 2023). "Ritlecitinib is a selective, covalent, irreversible inhibitor of Janus kinase 3 (JAK3) and the tyrosine kinase expressed in hepatocellular carcinoma (TEC) family kinases." (PMID 36977960, 2023).
lung carcinoma (10 papers, 2015 to 2025). "Another investigation highlighted the relationship between JAK2/JAK3 mutations in lung cancer and the expression of programmed cell death ligand-1 (PD-L1), implying potential benefits of immunotherapy for patients harboring JAK3 gene mutations." (PMID 38894865, 2024). "The JAK3 p.V722I germline mutation has been identified in a lung cancer patient with long-term benefit to anti-PD-L1 antibody atezolizumab." (PMID 29082853, 2017). "The JAK3 gene is confirmed to be associated with lung cancer." (PMID 33193633, 2020). "In lung cancer, JAK3 variants can promote PD-L1 induction in the tumor immune microenvironment and JAK3 activation may contribute to the long-term efficacy of PD-L1." (PMID 33083484, 2020). "In summary, miR-218 is capable to inhibit lung cancer cell proliferation and invasion, at least partially through repressing IL-6R and JAK3 genes expression." (PMID 28830450, 2017). "The newly-identified miR-218–mediated IL-6R and JAK3 genes silencing may facilitate a better understanding of the molecular mechanisms of lung cancer progression and present a new strategy to treat patients with lung cancer." (PMID 28830450, 2017). "Despite the small numbers in these rare lung cancer subtypes, SNV calling using the OncoMap database revealed previously undescribed SNV in FGFR1, CDKN2A, RB1, JAK3, and CTNNB1 for the large-cell type, a BRAF mutation for carcinoid, and an AKT1 mutation for adenosquamous carcinoma." (PMID 26076459, 2015). "exhibits significant anti-lung cancer potential by targeting key genes such as PIK3CG, SRC, and JAK3, as well as by modulating the PI3K-Akt signaling pathway and apoptosis-related genes." (PMID 40331978, 2025). "Network pharmacological analysis identified PIK3CG, SRC, JAK3, AKT2, and PRKCA as key potential targets of peiminine in lung cancer treatment." (PMID 40331978, 2025). "The results showed that the phosphorylation levels of Jak3 and Stat3 were induced by IFN-γ in lung cancer cells." (PMID 32038231, 2019). "We knocked out the Jak3 sequence using CRISPR-Cas9 technology and then transferred the Jak3–Leu905 mutant plasmid into the lung cancer cells." (PMID 32038231, 2019). "In order to correlate our findings with lung cancer prognosis in clinical settings, we analyzed the data from 1405 lung cancer patients and the gene expression of miR-218 host genes (SLIT2/SLIT3), IL-6, IL-6R, JAK3 and STAT3 in their tumor tissues." (PMID 28830450, 2017). "Additionally, the identified targets (PIK3CG, SRC, JAK3, AKT2, and PRKCA) may function as possible biomarkers for predicting lung cancer prognosis and guiding personalized therapy." (PMID 40331978, 2025). "Furthermore, CHIP assay confirmed that Stat3 did not bind to the IDO promoter region GAS in lung cancer cells in forced Jak3–Leu905 expressed cells." (PMID 32038231, 2019). "We further observed that ALDH1A1 positive cells had higher levels of IL-6R, JAK3 and phosphorylated STAT3, suggesting that the lower levels of miR-218 may be responsible for the upregulation of STAT3 signaling in ALDH positive lung cancer cells." (PMID 28830450, 2017).